CD68 (CD68 molecule)
Diseases named in the same sentence as CD68 in open-access papers (continued):
Sharing a sentence is not in itself a finding about the gene and the disease.
tumor (continued). "In our study, both pre- treatment and post-treatment CD68 staining in viable tumor correlated positively with the baseline SUVmax and negatively with percent viable tumor cells at resection (after chemotherapy)." (PMID 30999901, 2019). "In particular, cases with more CD68-positive cells at biopsy had fewer viable tumor cells at resection, suggesting a better response to chemotherapy." (PMID 30999901, 2019). "The tumor areas were also invaded by tumor associated macrophages (TAM), positive for CD68 and CD163 markers." (PMID 30326856, 2018). "The cytoplasmic granular structures of the tumor cells are lysozymes, as they show positive staining for CD68, and are reported to contain glycogen, a myelin-like structure, and a phospholipid membrane." (PMID 29329562, 2018). "In tumor tissue, we were able to show CD68/S100A9 double stained TAMs, suggesting their S100A9+ MDSC origin." (PMID 29484139, 2018). "S100A9+ MDSCs in PBMC were well correlated to tumor infiltrating CD68+ and S100A9+ cells, suggesting an origin of TAMs." (PMID 29484139, 2018). "PolyP-expressing mast cells were detected in close proximity with tumor cells and neutrophils, suggesting polyP expression by CD68+ mast cells among the stimuli which prime neutrophils to release NETs, in CRC." (PMID 29543850, 2018). "A panel of eight different markers was developed, including CD3, CD8, CD45RO, CD68, PD-1, PD-L1, FoxP3, as well as pan- cytokeratin and Sox10 as tumor markers." (PMID 30400835, 2018). "We evaluated CD68+ macrophage numbers in 10 cases of tumor-free peri-tumoral epithelia (TFE), 43 cases of low-grade dysplasia (LGD), 45 cases of high-grade dysplasia (HGD) and 110 cases of carcinoma (CA)." (PMID 29541395, 2018). "Administration of clodronate- (Cl2MDP) encapsulated liposomes partially depleted TAMs (defined as F4/80- and CD68-positive cells on immunohistochemical staining), resulting in reduced tumor growth in a murine Hepa1-6 cell-transplanted tumor model." (PMID 30410942, 2018). "Of the biomarkers beside PD-L1, CD8- and CD68-positive cells had the highest mean percentages in both tumor-nest (10.7%; 8.3%) and TME compartments (11.1%; 13.2%)." (PMID 29874226, 2018). "In the interfollicular zone (IFZ) of tumor-free cervical lymph nodes, a significant positive correlation between Gal3 expression and CD68 expression was detectable (Pearson correlation + 0.480; p = 0.020)." (PMID 30115022, 2018). "Multivariate analyses reported that CD68+ macrophage infiltration and tumor stage were strong and independent prognostic factors of HNSCC." (PMID 29541395, 2018). "The endpoints for which ROI were most representative of whole tumor were PD-1+ cell density in tumor stroma (0.98) and percent CD68+ macrophages in stroma (0.99)." (PMID 30400822, 2018). "CD68+ macrophages were reduced by 84% and 92% in CT‐26 tumours and murine rectum from metformin‐treated mice, respectively, indicating the successful depletion of macrophage by CLO." (PMID 29726618, 2018). "The results would have been more robust if more immune features from tumor microenvironments, such as CD8-TILs, PD-1-TILs, and CD68 tumor-associated macrophages, were included under the scope of our analysis." (PMID 29311707, 2018). "Macrophages exhibiting predominately the anti-inflammatory CD163/CD68 phenotype are known to be tumor-associated M2 macrophages, supporting the tumor, whereas M1 macrophages (CD68) act against the tumor." (PMID 29861851, 2018). "Patient tissues were stained with antibodies against CD68 for macrophages, pan-cytokeratin for epithelial tumor cells, and with either CSF1 or IL-34." (PMID 29719257, 2018). "CD68 positive macrophages were detectable at high density within the tumor, whereas osteoclasts and osteomacs were found at the tumor-bone interface, suggesting potentially differential functions for each population in the growing lesions." (PMID 29867776, 2018).
tumor (continued). "First, CD68+ macrophage numbers were evaluated in tumor samples derived from the four groups of mice and appeared to be significantly different (Kruskal–Wallis test, p = 0.006)." (PMID 29541395, 2018). "Breast G1/G2, G3 grade tumor and control specimens were immunostained for CD68, CD163, tryptase and CD31 to estimate total macrophages, M2-macrophages, mast cells, endothelial cells in the interstitial spaces and in periglandular position." (PMID 29854311, 2018). "In the monotherapy group, median OS was numerically longer, but not statistically significant, for patients with high PD-L1 in tumor cell, stroma or CD68 as compared to low PD-L1 tumors." (PMID 30400835, 2018). "By contrast, analysis of tumor from the same mice demonstrated that a significant number of CD68+ macrophages infiltrated into the tumor in HSC-NOG-hIL-6 Tg mice, whereas few infiltrates were detected in HSC-NOG non-Tg mice." (PMID 29456539, 2018). "Expression and absolute numbers of CD56, CD57, CD4 and CD68 were similar in resected tumor in both groups." (PMID 30229370, 2018). "First, CD68+ macrophage numbers are much higher in human tumors (max 110) than in mouse tumors (max 3,5), highlighting the deeper interaction between stroma and tumor cells in the human model." (PMID 29541395, 2018). "Of the examined immune markers, only the presence of a low level of tumor infiltration of CD68+ cells in the octogenarian age subgroup correlated with an increased risk of recurrence." (PMID 30216999, 2018). "Assessment by OS showed significant relationships for high PD-L1 in tumor (21m vs 8m median OS, p=0.036) and high PD-L1 in CD68 positive macrophages (20m vs 10m median OS, p=0.012)." (PMID 30400835, 2018). "Following dissociation of these tumor cells by mild trypsinization and staining for CD68 and Iba1, the cells were analyzed by flow cytometry in the high forward- and side-scatter range." (PMID 30041669, 2018). "M2-TAMs, which induce a tumor-promoting microenvironment, are characterized by co-expression of CD68 and CD163." (PMID 30065206, 2018). "In tumor resection specimens, the pan-macrophage marker CD68 showed a significant positive correlation with the other investigated macrophage markers (CD11c, CD163 and MRC1)." (PMID 30115022, 2018). "Collectively, these data indicated that TCs and CD68+ macrophages were the primary PD-L1-expressing cell types in the intra-tumour area of HCC tissues." (PMID 29921949, 2018). "We further found that percentages of blood S100A9+ MDSCs were well correlated with counts of S100A9+ cells and CD68 TAMs in tumor tissues." (PMID 29484139, 2018). "We conducted immunohistochemical analysis to detect human macrophages in HSC4-tumor using anti-CD68 or anti-CD163 antibodies, which are markers of macrophages or immunoregulatory macrophages, respectively." (PMID 29456539, 2018). "Here, we show for the first time that a low level of tumour cell E-cadherin is associated with low levels of immune cells (CD8+ T cells, CD68+ macrophages or FoxP3+ T-regs) in the tumour nest." (PMID 29416729, 2018). "In the tumor stroma, we observed heterogeneous pattern of claudin-2 expression in macrophages with the presence of CD68+/cl2−, CD68+/cl2+ (see Fig. 1D2), CD163+/cl2− and CD163+/cl2+ cells (see Supp Fig.3B1 and C)." (PMID 29134439, 2018). "CD68+ macrophage numbers were evaluated in 10 cases of tumor-free peri-tumoral epithelia, 43 cases of low-grade dysplasia, 45 cases of high-grade dysplasia and 110 cases of carcinoma." (PMID 29541395, 2018). "We also found a decrease in the number of aromatase-positive, CD68-positive macrophages within the tumor microenvironment, suggesting that metformin targets the immune microenvironment in addition to improving whole-body metabolism." (PMID 29898754, 2018). "A smaller number of CD68+ macrophages and FoxP3+ T–regs were observed with roughly equal distributions between tumour nest and stroma." (PMID 29416729, 2018).
tumor (continued). "In majority of previous studies, CD68 was used as a common biomarker for all macrophages in tumor samples." (PMID 29861872, 2018). "Conversely, accumulation of M1‐like TAMs (CD68+/iNOS+) was apparently increased in 200 and 300 mg/kg day metformin‐treated 4T1 tumours." (PMID 29726618, 2018). "In radiotherapically treated tumors, macrophages are detectable by immunohistochemical examination, but, areas of residual/recurrent neoplasia contain a smaller number of CD68 positive cells in comParison to other areas." (PMID 29584702, 2018). "CD68+ tumor macrophages were distributed throughout the tumor and the stromal compartment, both of which were positive for FBLN5." (PMID 29581841, 2018). "CD3, CD31 and CD68 tumour fractions correlated moderately to strongly with both central tendency and heterogeneity parameter values." (PMID 28550313, 2017). "EpCAM, K19 or CD133 expression also showed a significant correlation with those of tumor stromal CD68 (+)/CD163 (+) TAMs and IL-6 (+) stromal cells." (PMID 28114366, 2017). "Although CD68 IHC was performed to eliminate macrophages, in some instances, it was difficult to differentiate between tumor cells and macrophages." (PMID 29049375, 2017). "The Gal3/CD68 expression ratio in the epithelial fraction of T2 oscc tumor resection specimens was significantly higher than in T1 cases (median value 0.73 and 0.30, respectively, p = 0.002)." (PMID 29284429, 2017). "The entirety of the tumor is evaluated on low power allowing for clusters of dense brown anti-CD68 staining to be identified." (PMID 28475599, 2017). "The inducible and specific depletion of CD68+ cells offers flexibility to investigate the role of TAMs at different stages of tumor development, growth, metastasis and during anti-cancer therapy treatment." (PMID 29220404, 2017). "Inspection of the images readily revealed infiltrating clusters of iron(III)+ HLMs corresponding to CD68+ macrophages in the Myc-CaP tumor sections." (PMID 28912459, 2017). "In biopsy and tumor resection specimens, the number of Gal3 positive cells as well as the ratio between Gal3 expressing cells and CD68 positive macrophages was higher in T2 oscc cases compared to T1 cases." (PMID 29284429, 2017). "We found that in the epithelioid tumours, high CD4+ and CD20+ counts, and low FOXP3+, CD68+ and NP57+ counts linked to better outcome." (PMID 28817839, 2017). "α-SMA (+) CAFs, CD68 (+) tumor stromal TAMs, and IL-6 (+) tumor stromal cells were significantly higher in moderately/poorly differentiated HCCs, compared to well differentiated HCCs (P <0.05 for all)." (PMID 28114366, 2017). "Regarding TAMs, the expression of CD68 (+) or CD163 (+) tumor stromal TAMs significantly increased with progression of multistep hepatocarcinogenesis (both, P <0.001) from LGDN to pHCC." (PMID 28114366, 2017). "We determined PD-L1 expression, numbers of CD3+ T cells, CD20+ B cells, CD68+ monocytes/macrophages, Foxp3+ regulatory T cells and CD163+ tumor-associated macrophages by immunohistochemistry in 103 patients." (PMID 29190964, 2017). "Since digital quantification of TILs can solve this problem, we first established the pipeline of counting CD45+, CD4+, CD8+ and CD68+ TILs inside and outside tumor areas that were manually outlined." (PMID 28923066, 2017). "They showed that it is the tumor itself which stimulates the expression of HLA-G/sHLA-G on both cancer cells and infiltrating immune cells, especially CD68+ macrophages and CD8+ T cells." (PMID 28376925, 2017). "In accordance with this modulation of gene expression, IL-15 treatment also reduced the amount of CD68+ and F4/80+/CD68+ cells in the tumor mass, indicative of reduced activation of GAMs." (PMID 29286001, 2017). "By contrast, HPV ̄ OPSCC have lower CD8+ T cell but higher densities of CD8+ PD-1+ T cells and CD68+PD-L1+ macrophages in their stroma compared to HPV+ tumours." (PMID 28122336, 2017).
tumor (continued). "High Gal3 expression as well as a high Gal3/CD68 ratio correlated with tumor size and parameters of malignancy." (PMID 29284429, 2017). "In biopsy and tumor resection specimens, the number of Gal3 positive cells as well as the Gal3/CD68 ratio were significantly (p < 0.05) higher in T2 oscc compared to T1 cases." (PMID 29284429, 2017). "Although M1 macrophages has anti-tumor function, our data shows markers including CD68, CD86, TLR2 and TLR4 are correlated with CD163 too." (PMID 29152078, 2017). "We also analyzed the relation between PD-L1 expression and three key indicators of the intra-tumoral immune response, CD8, CD4, and CD68 tumor infiltrating leucocytes (TIL)." (PMID 28881675, 2017). "Immunohistochemistical staining of tumor sections revealed an increase in recruitment of cells positive for CD68, a marker for macrophages/immune cell types, to the surgical site (50% vs 10%, debulking vs non-debulking, respectively)." (PMID 28076333, 2017). "In keeping with previous reports, large numbers of CD68+ macrophage were present and these were more widely distributed throughout the tumour than T cells." (PMID 28931051, 2017). "Wild-type and GRP78 heterozygous tumor-bearing mice were treated with tamoxifen and fixed tumors were stained for CD68 and CD80." (PMID 29113324, 2017). "Consecutive tumor sections IHC-stained for CD68 (macrophage marker) and TIM3 suggest that the “other immune cells” are TIM3+ macrophages." (PMID 29163490, 2017). "AT1-tumors generally grew as a small tumor mass with the tumor cells lying close to each other surrounded and invaded by inflammatory cells, mainly CD68+ macrophages, lymphocytes and some PMNs." (PMID 29073272, 2017). "In the late time, the presence of CD68+ cells outside the tumor core was also observed suggesting that CD68+ cells start to be recruited within the GB tumor in good agreement with the literature in GB and other tumors." (PMID 29069812, 2017). "The reason for this finding is most likely that the predominant subtype of TAM in the tumour microenvironment is leaning towards pro-tumour polarisation, thus making up for a large part of the CD68+ TAM population." (PMID 28673320, 2017). "By contrast, in the TRAMP-C2 tumors the CD68+ macrophages were found abundantly both at the tumor margins and within the tumors, although the iron(III)+ HLMs were scarce and when found were localized to outer margins of the tissue." (PMID 28912459, 2017). "We are of the opinion that not covering of all M2 phenotypes should not have a significant influence on its practical usefulness and the intensity of CD68+/iNOS− macrophage infiltration within the tumor stroma seems to be a good prognostic factor in CRC." (PMID 28343267, 2017). "In HCC, we and other groups have demonstrated that the number of CD68+ Mφs in tumor o was negatively correlated with patient prognosis." (PMID 28202073, 2017). "Counting the total number of iron(III)+ macrophages and CD68+ macrophages per mm2 of the whole tissue cross-section area showed both total HLMs and CD68 macrophages increased in frequency from tumor<liver<spleen." (PMID 28898277, 2017). "The density of CD68+ cells was 7.2±3.8% and 11.4±2.4% in the tumor mass early and late after X-ray treatment, respectively." (PMID 29069812, 2017). "In all cases, the analysis revealed throughout the tumor proliferation a low number of T cells, CD3+, and CD8+ and of tumor‐associated macrophages (TAM), CD163+, and/or CD68+, distributed around the vessels." (PMID 28627792, 2017). "PD-L1 is expressed by many cell types and in the tumor microenvironment PD-L1 is predominantly expressed by CD68 macrophages." (PMID 28881675, 2017). "We did not detect any significant difference in the staining intensity of CD31 and CD68 in the tumor infiltrate between the TLR4 tumors and control tumors." (PMID 28982115, 2017).
tumor (continued). "Alpha smooth muscle actin (α-SMA), CD68 and CD31 were considered as the specific biomarkers of cancer-associated fibroblasts (CAF), tumor associated macrophages (TAM) and neovascular endothelial cells, respectively." (PMID 29156791, 2017). "To assess possible virus replication in tumor-associated microglia/macrophages (TAM), we performed CD68-FISH staining." (PMID 28967558, 2017). "This contradicts the suggestion that CD68 macrophage expression of PD-L1 serves as a homeostatic mechanism which inadvertently provides an immune privileged milieu encouraging tumour growth." (PMID 28122336, 2017). "The Gal3/CD68-ratio in the epithelial compartment of G3 oscc tumor resection specimens was significantly higher compared to G2 cases (median value 1.31 and 0.52, respectively, p = 0.008)." (PMID 29284429, 2017). "The whole analyzed specimen area (epithelial + stroma) in T2 oscc tumor resection specimens also showed a significantly higher Gal3/CD68-ratio than in T1 cases (median value 0.58 and 0.24, respectively, p = 0.010)." (PMID 29284429, 2017). "Samples were evaluated for the presence of TAMs by counting the number of CD68 positive cells in three hot spot high power fields (hpf) per tumor." (PMID 28475599, 2017). "Gal3/CD68 ratio was seen in the epithelial tumor compartment as well as the whole analyzed specimen area including stroma and epithelium." (PMID 29284429, 2017). "In comparison, only a subset of macrophages (CD68+) in the primary tumour displayed putative M2 markers (CD163+ or COX-2+)." (PMID 28417956, 2017). "CD68 stained tumour fractions correlated negatively with mean and median R1 pre O2 and median R1 post O2 and positively with mean and median ADC (P < 0.050)." (PMID 28550313, 2017). "We found its expression to be significantly related with CD3+, CD20+ and CD68+ intra-tumor immunocytes." (PMID 29190964, 2017). "PD-L1 expression was identified on tumor cells in five (19%) primary CM and on stromal cells (mainly CD68+CD163+ M2 macrophages) in 16 (59%) cases." (PMID 28903377, 2017). "We enumerated MΦ infiltration in a tumor by immunohistochemical analysis using the anti-human CD68 antibody." (PMID 29095438, 2017). "Our data indicates that patient tumors with strong SUSD2 staining had increased CD68 staining of macrophages in the tumor." (PMID 28475599, 2017). "In detail, CD8 was highly expressed in both groups while CD56 and CD68 were only occasionally expressed in non-tumor liver both in controls and rats treated with Vidatox." (PMID 28322221, 2017). "High levels of MHCII were also associated with higher CD8, CD4, and CD68 TIL and this was statistically significant for epithelium and stromal areas across tumor groups (i.e. all cases), and in both Luminal A, and Basal-like tumors." (PMID 27058619, 2017). "Next, we evaluated ZEB1 expression by tumor cells near in pseudopalisades and perinecrotic areas from seven additional cases in colabeling with CD68 to discriminate macrophages populating the necrotic region." (PMID 28945795, 2017). "CD68 (+) or CD163 (+) tumor stromal TAMs were all enriched together with EpCAM, K19 and CD133 expression (P <0.05 for all)." (PMID 28114366, 2017). "The pooled HR showed that high density of CD68+ cells in the tumor islet predicted better OS (HR = 0.50, 95% CI = 0.30 ~ 0.85, P = 0.01; I2 = 83%, P = 0.0005)." (PMID 27144518, 2016). "The expression levels of CD68-positive macrophages (P = 0.009) and CD163-positive macrophages (P = 0.015) in tumor nest was significantly associated with poor prognosis." (PMID 26769084, 2016). "The result demonstrated that tumor stroma densities of CD68 and IL-13 were independent prognostic factors for patients’ overall survival (p < 0.01)." (PMID 26771842, 2016). "A histological examination showed that the number of tumor-infiltrating CD68+ macrophages was reduced after sorafenib therapy." (PMID 27203677, 2016).